DEFB119 (defensin beta 119)
Description:
Has antibacterial activity.
Synonyms: DEFB-19; DEFB-20; DEFB120; DEFB20; ESC42-RELA; ESC42-RELB
Tractability: Antibody: UniProt places it where antibodies can reach, with high confidence; UniProt predicts a signal peptide or a membrane-spanning region; its Gene Ontology location is reachable by antibodies, with medium confidence.
Gene: Protein-coding gene on chromosome 20 (31,377,164 to 31,390,590, reverse strand). Ensembl gene ENSG00000180483.
Subcellular location: Secreted
Subcellular location (Human Protein Atlas): Mitochondria; Predicted to be secreted
Pathways (Reactome):
Immune System: Beta defensins; Defensins
Gene Ontology:
Biological process: defense response to Gram-negative bacterium; defense response to Gram-positive bacterium
Cellular component: extracellular region
Genetic constraint (gnomAD): Loss-of-function variants: 5 observed, 5.25 expected, observed/expected ratio (o/e) 0.95, 90% interval 0.49 to 1.77. That is too few expected variants to judge how well the gene tolerates losing a copy. Missense variants: 113 observed, 106.54 expected, observed/expected ratio (o/e) 1.06, 90% interval 0.91 to 1.24. Synonymous variants: 29 observed, 35.4 expected, observed/expected ratio (o/e) 0.82, 90% interval 0.61 to 1.12.
Homologues: Orthologues: dog DEFB119 (70% identical), pig DEFB119 (68% identical), mouse Defb19 (64% identical), guinea pig DEFB119 (62% identical), rat Defb24 (62% identical). Paralogues in human: DEFB123 (27% identical), DEFB115 (25% identical), DEFB121 (25% identical), DEFB116 (24% identical), DEFB118 (24% identical), DEFB124 (24% identical), DEFB125 (24% identical), DEFB127 (23% identical), DEFB129 (23% identical), DEFB108B (21% identical), DEFB128 (21% identical), DEFB134 (21% identical), and 7 more.
Diseases named in the same sentence as DEFB119 in open-access papers:
DEFB119 is named in the same sentence as 1 disease in open-access papers, as found by Europe PMC text mining. Sharing a sentence is not in itself a finding about the gene and the disease. The quoted sentences say what the papers report.
tumor (2 papers, 2018 to 2020). "Conversely, some genes are associated with both tumor status and survival (MUC4 for HNSC, TMPRSS11F, SLC6A18, and DEFB119 for LGG)." (PMID 32625238, 2020).